IL6 (interleukin 6)
Diseases named in the same sentence as IL6 in open-access papers (continued):
Sharing a sentence is not in itself a finding about the gene and the disease.
tumor (continued). "In a primary neuroblastoma without MYC-N amplification, CD1d-expressing CD68+ tumor-associated macrophages (TAMs) stimulate tumor growth through production of IL-6, and a high TAM gene signature is associated with poor prognosis." (PMID 30158927, 2018). "Further, cytokines secreted by adipose tissue like IL-1β, IL-6 and IL-8 have been implicated in tumor progression by stimulating tumorigenic pathways in cancer cells, such as TNFα and NF-κB signaling." (PMID 29930291, 2018). "The IL-6 levels secreted from M2 macrophages and A549 cells decreased after USP24 knockdown, suggesting that USP24 upregulation in the tumor-associated microenvironment and cancer cells during tumorigenesis increased IL-6 expression." (PMID 30266897, 2018). "Mechanistically, the HER2‐p38 signalling axis drives progression of SPRY2‐deficient tumours to an androgen autonomous castration‐resistant state by inducing IL6 cytokine axis." (PMID 29540470, 2018). "Chronic inflammation has been confirmed to be strongly associated with tumor invasion, migration and metastasis through increased secretion of pro-inflammatory cytokines, such as IL-2, IL-6, tumor necrosis factor-α and so forth." (PMID 30513726, 2018). "IL-6 in particular activates STAT3 signaling in tumor cells and high STAT3 phosphorylation is associated with a poor prognosis in many types of cancers." (PMID 29883385, 2018). "Overexpression of IL-6 is also associated with tumor progression by inhibition of apoptosis, stimulation angiogenesis and reinforcing tumor drug resistance." (PMID 29416610, 2018). "Namely, tumor-associated ECs express and release IL-6, jointing with CSF-1 in the microenvironment, induces HIF-2α-dependent arginase-1 expression through activation of PPAR-γ, leading to macrophage alternative polarization and GBM progression." (PMID 29422647, 2018). "The data consistently showed that chemerin targeted tumor cells and tumor-associated endothelial cells, the major source of GM-CSF and IL-6, via interaction with CMKLR1 and CCRL2, reducing expression of inflammatory cytokines and inhibiting NF-κB activation." (PMID 30555465, 2018). "Our findings suggest G3BP1 as a novel mediator of RCC tumor progression and further extends the current knowledge about IL-6/STAT3 associated mechanism in RCC carcinogenesis." (PMID 29717134, 2018). "IL-6 has been linked with malignancy across a number of different tumour types, with its importance being related to downstream signalling via STAT3 activation." (PMID 29256156, 2018). "In the current study, high IL-6 expression was associated with good prognostic variables, i.e. lower tumour size, lower grade, and lower NPI value." (PMID 29256156, 2018). "Here we show that in premature senescent tumor cells trabectedin causes a marked decrease in the expression of proinflammatory cytokines (IL-6, IL-8, TNF-alpha), which play critical roles in tumor growth and metastasis." (PMID 29731994, 2018). "We did a systematic review of studies (1993–2018), to assess the clinical use of IL-6 as a diagnostic, prognostic or predictive tumor biomarker or as a potential therapeutic target." (PMID 30038723, 2018). "The correlation of IL-6 and PEc is fortified by the fact that both these factors possess similar oncogenic role that is associated with tumor progression and metastases." (PMID 30134795, 2018).
tumor (continued). "Tumor exosomes have been shown to activate MDSCs by inducing autocrine IL-6 production, which is further linked to STAT3 activation and response to chemotherapy." (PMID 30383833, 2018). "Despite the difference in aggressiveness of tumor development, our data clearly demonstrated the IL‐6 role in controlling the susceptibility of CRPC tumors to NK cell cytotoxicity." (PMID 28865178, 2018). "Another important group of immune-associated genes regulated by anisomycin included KITLG, IL-6, IL-32, and IL-3RA, which encode cytokines and cytokine receptors to mediate potential survival signals or growth signals in tumour cells." (PMID 30006566, 2018). "Previous studies have shown that IL-6 is secreted not only by the tumor-associated microenvironments but also by the tumor itself." (PMID 30266897, 2018). "Along with altered circulating cholesterol levels, in mice bearing SPRY2‐deficient tumours, serum IL6 levels were also significantly raised following ADT." (PMID 29540470, 2018). "As expected, in subcutaneous tumor models, macrophage TgMGLL largely potentiated mRNA levels of TNFα, IL-6, and IFNγ in tumor-associated CD8+ T cells, and this effect was prevented by additional macrophage TgCB2." (PMID 29968710, 2018). "Lactate also acts as an important signaling molecule to promote the production of cytokines such as IL-23 and IL-6 contributing to tumor-associated inflammation." (PMID 30061885, 2018). "Tumor-associated macrophages secrete a number of soluble factors, such as cytokines, comprising interleukin (IL)-6, IL-10, sustaining glioblastoma proliferation and promoting neovascularization." (PMID 30279357, 2018). "Higher circulation levels of IL-6 are also associated with tumor differentiation, local invasion, and poorer survival among patients with GBC21." (PMID 29618736, 2018). "MDSCs are a heterogeneous population of cells that can be induced by tumor-associated inflammation, including autoimmune related cytokines such as IL-1β and IL-6." (PMID 29643991, 2018). "Futhermore, IL-6 deletion did not affect iNOS expression, but remarkedly inhibited arginase-1 expression in tumor-associated F4/80+ macrophages, supporting the important role of endothelial IL-6 in macrophage alternative activation." (PMID 29422647, 2018). "In line with this, high IL-6 tumor expression was associated with tumor progression and reduced survival in HCC patients." (PMID 29899223, 2018). "These two publications suggest that NLRX1 functions as a tumor suppressor by decreasing cancer-associated inflammation (IL-6 and TNFα) through effects on NF-κB signaling." (PMID 29535731, 2018). "Multiple genomic studies on both primary cell lines and tumor specimens have confirmed excessive IL-6 production and secretion as a hallmark of IBC." (PMID 28607534, 2017). "To further investigate the mechanism of upregulation of SOD-2 in AFG1-induced lung tumor, we treated A549 cells and MΦ-THP-1 cells with AFG1, TNF-α and/or IL-6 to mimic the AFG1-induced tumor-associated inflammatory microenvironment in vitro." (PMID 28801561, 2017). "Activated tumor-associated macrophages secrete G-CSF, IL-6 and VEGF, promoting angiogenesis and creating an inflammatory niche." (PMID 29245929, 2017). "It has also been observed that IL-6 negatively affects the expression of genes associated with tumor suppression and anchorage-dependence growth in colonic epithelial cells in vitro." (PMID 28558708, 2017).
tumor (continued). "To explore the mechanism underlying the role of CAFs on tumor metastasis, we investigated the effect of CAFs on IL-6/STAT3 signaling pathway." (PMID 29100297, 2017). "More significantly, IL-6 production, which has been considered to be closely associated with tumorigenesis in tumor microenvironment, was impaired." (PMID 28243242, 2017). "The serum visfatin concentration in HCC patients was positively correlated with AFP (r=0.595, P<0.001) and IL-6 (r=0.261, P<0.015) and was also associated with tumor size and tumor node metastasis stage." (PMID 28178643, 2017). "Previous studies have also shown a tumor-promoting role for CAFs via IL-6 secretion and an association between IL-6 secretion and upregulation of ECM-degrading enzymes (e.g., cathepsin B, MMPs, and uPA)." (PMID 28506312, 2017). "In contrast to the effects of IL-6 on tumor-associated immune cells, IL-6 is also a direct critical driver of tumor growth and metastasis." (PMID 28186964, 2017). "To definitively assess the impact of IL-6 on NB-Tag tumor development, we generated IL6-deficient double transgenic mice (NB-Tag/IL6KO), and studied their tumor growth kinetics." (PMID 29207662, 2017). "IL-6 overexpression was described in several malignancies and was associated with advanced disease and tumor progression." (PMID 29163540, 2017). "Particularly, interleukin-6 (IL-6) expression, which is closely associated with the cancer malignant behaviors, was significantly dampened in tumor tissues." (PMID 28243242, 2017). "Tumor infiltration by the proinflammatory Th17 T cells is associated with increased Th17‐associated cytokines IL‐23, IL‐17, IL‐1β, and IL‐6." (PMID 28599100, 2017). "Sustained production of pro-inflammatory cytokines, such as TNF-α, IL-6 and IL-1β, results in chronic inflammation, which, in turn, increases cancer risk, tumor development and progression." (PMID 29044191, 2017). "Data provided in this review demonstrate that most proinflammatory cytokines (IL-1, IL-4, IL-6) produced by either host immune cells or tumor cells themselves are associated with tumor malignancy in patients and animal cancer models." (PMID 28927416, 2017). "Th1 cytokines, including IFN-γ, IL-2, and TNF-α, enhance the cytotoxicity of CIK cells, whereas Th2 cytokines like IL-6 and IL-10 is associated with tumor immune escape." (PMID 28404886, 2017). "A growing body of evidence showed that inflammatory cells usually produce large amounts of pro-tumorigenic cytokines, such as TNF, Interleukin-6 and Interleukin-23, which cause cell proliferation and tumor progression in colorectal cells." (PMID 29657291, 2017). "Medium derived form CD44−/CD90+ caused significant downregulation in expression of IL6 (p=0.0001) in CD44+/CD90− cells (anticipated epithelial tumor cells) compared with medium derived from CD44+/CD90−." (PMID 29029509, 2017). "The C26 tumor model is well established and characterized by a profound increase of pro-inflammatory cytokines such as IL-6 and TNF-α, severe body weight loss and only a moderate decrease in food intake compared to other CACS tumor models." (PMID 28475119, 2017). "IL-6 is an important tumor-promoting protein associated with stress responses, inflammation and angiogenesis." (PMID 28859644, 2017). "It activates pro-inflammatory genes (COX-2, iNOS, TNF-α, IL-1, and IL-6) in tumor and tumor-associated cells and surrounding tissue, as well as antiapoptotic (Bcl-2, Bcl-X) and proangiogenic molecules (vascular endothelial growth factor)." (PMID 28487844, 2017). "IL-6 is a well-known important proinflammatory cytokine tightly linked to increased cancer cell proliferation and tumor progression." (PMID 28036277, 2017). "We previously have reported that tumor-associated endothelial cells lining tumor blood vessels express more IL-6 than the tumor cells themselves." (PMID 29245982, 2017).
tumor (continued). "Strikingly, efficacious tumour immunosurveillance due to tumour-specific CD4 + T cells was consistently related to increased local concentrations of both proinflammatory (IL-6, IL-1α, and IL-1β) and Th1-associated cytokines (IL-2, IL-12, and IFN-γ)." (PMID 29089667, 2017). "Increasing evidences have suggested that IL-6 plays a critical role in modulating the function and activity of tumor-associated immune cells." (PMID 28186964, 2017). "Mechanistically, high MAP17 levels increase the recruitment of tumor/inflammation associated macrophages, MDSCs, mast cells, and neutrophils to the target tissue, by increasing IL-6 locally and probably other cytokines or chemokines." (PMID 29228712, 2017). "We found that DEK was associated with advanced tumor stage, increased hazard of death, and interleukin IL6 expression in HPV16+ disease." (PMID 28423581, 2017). "IL-6 is generally known to be secreted by tumor-associated fibroblasts and to create an environmental niche for cancer progression." (PMID 28784136, 2017). "IL-6 can upregulate DNA methyltransferases, resulting in modification of the methylation status of genes associated with tumor suppression." (PMID 28558708, 2017). "IL-6 overexpression in exercising tumor-bearing mice was resistant to muscle mass loss and metabolic changes." (PMID 28785374, 2017). "Some proinflammatory cytokines (such as TNF-α, IL-1, and IL-6) that are encoded by target genes of the NF-κB pathway contribute to inflammation-related tissue damage and are associated with tumor development and progression." (PMID 28852270, 2017). "While TAMs are observed in primary tumors of children with high-risk disease, the mechanism of their contribution to tumor growth and the relative role of IL-6 in STAT3 activation are not clearly understood." (PMID 29207662, 2017). "IL-6 is the major cancer-promoting cytokine in the setting of chronic colitis-associated carcinoma, which induces several pathways leading to tumor growth." (PMID 28350804, 2017). "Overexpression of either IL-6 or IL-8 partially rescued SHMT1 loss-induced tumor growth inhibition and migration." (PMID 28288142, 2017). "Various studies have reported that elevated IL-6 levels are associated with advanced tumor stages, increased tumor size, metastasis, and decreased survival of CRC patients." (PMID 28725043, 2017). "Tumour-associated myeloid cell production of IL-6 promotes colon tumour cell proliferation and protection from apoptosis through activation of STAT3." (PMID 28210073, 2017). "This was associated with reduced tumor cell proliferation and a significant reduction in IL-6, pSTAT3 and TNFα levels." (PMID 28416734, 2017). "It has been widely accepted that the accumulation of MDSC is driven by tumor-derived inflammatory cytokines and associated signaling pathway, notable IL-6 and its downstream STAT3 signal." (PMID 29100353, 2017). "In animal studies, IL-6 trans-signaling is linked to tumor development in inflammation-induced colorectal and pancreatic cancer." (PMID 28676747, 2017). "Activation of S1PR4 signaling on human and murine tumor-associated macrophages (TAMs) by apoptotic tumor cell-derived S1P leads to the production of tumor-promoting cytokines, including IL-6 and IL-10." (PMID 28848247, 2017). "We have shown, that the increase of the resistance of tumor cells is partially caused also with IL-6 and IL-8." (PMID 26759169, 2016). "Next, WCUP administration prevented increases in serum IL-6 levels and muscular E3 ligase levels caused by CT-26 tumor burden, resulting in the recovery of skeletal muscle mass and lean body mass." (PMID 27064118, 2016). "Some mechanisms responsible for dysfunction of immune cells are directly mediated by factors produced by tumors, whereas others result from tumor-associated microenvironment, including IL-1β, IL-4, IL-6, IL-10, IFN-γ and TGF-β." (PMID 27391078, 2016).
tumor (continued). "Inversely, the loss of Gli-1 function diminishes IL-6 signaling from tumor-associated fibroblasts, which prevents progression of pancreatic precursor lesions to advanced stages." (PMID 26716648, 2016). "Our results would thus be consistent with an antigen-driven activation of circulating macrophages that are induced to secrete inflammatory cytokines, especially IL-6 and TNFα, potentially associated with an anti-tumor effect." (PMID 27662661, 2016). "IL-6 is mainly secreted by tumor-infiltrating lymphocytes and tumor-associated macrophages, explaining the increased expression of DNMT1 in the inflammatory stromal subtype." (PMID 27071379, 2016). "Taken together, our data suggest that IL-6 secreted in tumor environment is associated with the metastatic potential of human OS." (PMID 27851822, 2016). "Tumor-associated macrophages were observed to upregulate the expression of B7-H4 through IL-6 and IL-10 in the tumor microenvironment." (PMID 27626488, 2016). "Further, we find that the stromal-derived senescence-associated secretory phenotype factor interleukin-6 orchestrates both increases in suppressive myeloid cells and their ability to inhibit anti-tumour T-cell responses." (PMID 27272654, 2016). "A variety of cytokines secreted by Bregs have been implicated in the suppression of anti-tumor immunity including IL-10, IL-35, IL-6, and TGF-β." (PMID 27437104, 2016). "Higher IL‐6 levels were associated with larger tumor size, advanced tumor stage, increased tumor occurrence, and decreased survival of CRC patients." (PMID 26799163, 2016). "Related to cancer cachexia, PDTC decreased tumor NF-κB DNA binding, which led to reduced circulating IL-6 and the attenuation of muscle mass loss in colon-26 (C26) tumor-bearing mice." (PMID 27449092, 2016). "Numerous studies indicate that IL-6 and its related signalling pathways have been identified to contribute to proliferation, migration, and invasion of various tumour cells and its expression is associated with poor prognosis in many types of cancers." (PMID 27034885, 2016). "These anti-IL-6 receptor antibodies neutralize the effects of tumor-derived IL-6 and suppress expansion of cancer-associated MDSCs." (PMID 27029037, 2016). "The possibility that stromal-derived SASP factors, including IL-6, mediate the establishment of chronic inflammation that predisposes a tissue to tumour outgrowth is intriguing." (PMID 27272654, 2016). "In NPC, higher expression of IL-6 expression in tumor tissues was associated with poorer patient survival." (PMID 27487154, 2016). "Recent studies suggest that tumor-associated macrophage-produced IL-6 is an important mediator within the tumor microenvironment that promotes tumor growth." (PMID 27006530, 2016). "In three studies, increased levels of IL-1β were associated with poor prognosis: metastasis, shorter survival, and when analysed together with IL-6, was associated with poor overall survival and tumor progression." (PMID 27170998, 2016). "In cutaneous melanoma, IL-6 expression is detectable at the early nevi stage, and its level dramatically increases as the tumour invades deeper into the underlying dermis." (PMID 27191257, 2016). "In their study, a strong connection existed between serum IL-6 levels and excessive weight loss, invasiveness of the tumor to surrounding tissues, lymph node involvement, and impossibility of complete tumor resection." (PMID 26082902, 2015). "PDT with different photosensitizers generally induces IL-6 transcription in and subsequent secretion by tumor cells, which commonly is associated with improved PDT outcome." (PMID 26307977, 2015). "In a subsequent study, the same group found that PDT with 2-(1-hexyloxyethyl)-2-devinyl pyropheophorbide-a (HPPH) caused an increase in intratumoral as well as circulating IL-6 levels in EMT-6 tumor-bearing mice." (PMID 26307977, 2015).